THY1 (Thy-1 cell surface antigen)
Diseases named in the same sentence as THY1 in open-access papers (continued):
Sharing a sentence is not in itself a finding about the gene and the disease.
lung fibrosis (continued). "In contrast, TGF-β and interleukin-1 (IL-1) are important players in the development of lung fibrosis, further suggesting an inhibitory role of Thy-1+ (CD90+) fibroblasts in the process of lung fibrosis." (PMID 36747131, 2023). "In contrast to lung fibrosis, Thy-1–KO mice had attenuated skin fibrosis in both bleomycin and tight skin-1 murine models." (PMID 36066980, 2022). "Given these opposing findings, it is of particular interest that we demonstrated opposite effects in skin and lung fibrosis in Thy-1–KO mice." (PMID 36066980, 2022). "On the other hand, Thy1−/− mice showed more exacerbated lung fibrosis by 25% than wild-type mice, which was consistent with previous findings of the inhibitory effect of Thy1 on activation of lung fibroblasts." (PMID 36358290, 2022). "The role of Thy-1 has been studied in lung fibrosis where it has been reported that Thy-1 plays an important role in lung fibrogenesis in IPF in which patients have been reported to have decreased Thy-1 expression." (PMID 36066980, 2022). "We confirmed these opposing findings in our s.c. bleomycin model: while Thy-1–KO mice had attenuated skin fibrosis, they demonstrated exacerbated lung fibrosis under chow conditions." (PMID 36066980, 2022). "Thy-1 is silenced in lesional fibroblasts in IPF (Idiopathic Pulmonary Fibrosis), and its expression in murine lung fibroblasts is decreased with progression of experimental bleomycin induced lung fibrosis." (PMID 34966784, 2021). "Thy-1 is chronically lost in pulmonary fibrosis and other fibrotic disorders by epigenetic silencing through the hypermethylation of the promoter region of its coding gene TYHY1, and such repression is considered a major driving process of pulmonary fibrosis." (PMID 34359678, 2021). "It has been reported that Thy-1 null c57BL/6 mice were more prone to develop severe lung fibrosis after bleomycin treatment." (PMID 30859101, 2019). "Elevated αvβ3 staining was observed in both Thy-1 KD cells and in Thy-1 null mice treated with bleomycin to induce lung fibrosis, implicating strong correlation between lung fibrogenesis, Thy-1 loss and dysregulated integrin αvβ3 signaling." (PMID 30859101, 2019). "Normal lung fibroblasts, both in mice and in humans, are predominantly Thy-1-positive and their presence appears to limit pulmonary fibrosis." (PMID 26495280, 2015). "Our detection of the downregulation of myofibroblast Thy1 expression as fibrosis evolves is consistent with findings in several other studies of an inverse correlation between Thy1 expression on fibroblasts and the evolution of lung fibrosis." (PMID 26300593, 2015). "Our results suggest that Thy-1-related lung fibroblast phenotype transformation contributes to the pathogenesis of LPS-induced lung fibroblast proliferation and pulmonary fibrosis." (PMID 23305530, 2013). "One such paradigm has been illustrated by the predominance of Thy-1− lung fibroblasts in pulmonary fibrosis accompanied by inflammation." (PMID 20657842, 2010). "In a word, a group of fibrosis-related genes, including TGF-β1, CXCL10, COX-2, and Thy-1, may be potential targets for epigenetic therapy of pulmonary fibrosis." (PMID 38915445, 2024). "The reduced apoptosis of Thy-1-negative myofibroblasts resulted in the persistence of myofibroblasts during the resolution phase of bleomycin-induced lung fibrosis, was associated with collagen accumulation, and extended lung fibrosis in Thy-1-deficient mice." (PMID 36768219, 2023). "Indeed, in an in vivo model of lung fibrosis, the administration of soluble Thy-1 therapeutically inhibits integrin-mediated fibrosis." (PMID 38099295, 2023). "Importantly, in human idiopathic pulmonary fibrosis, activated fibroblasts within the fibroblastic foci lose Thy-1 expression." (PMID 36768219, 2023). "Deletion of Thy1 in Thy1−/− mice exacerbated bleomycin-induced lung fibrosis." (PMID 36358290, 2022).
lung fibrosis (continued). "Similarly, Thy-1 deficit in an in vivo lung fibrosis mouse model is restored by administrating soluble Thy-1, showing that treatment with soluble Thy-1 therapeutically inhibits integrin-mediated fibrosis." (PMID 35186924, 2022). "Moreover, treatment with soluble Thy-1 has shown to reduce bleomycin-induced lung fibrosis severity." (PMID 36066980, 2022). "Bleomycin leads to myofibroblast differentiation, and Thy-1–deficient mice show impaired apoptosis of myofibroblasts leading to nonresolving lung fibrosis." (PMID 36066980, 2022). "RT-qPCR and western blot analyses suggested that compared with control mice, mRNA expression of YY1 and HSF1, and expression of miR-214 in the mice with bleomycin-induced pulmonary fibrosis were significantly increased and the expression of THY1 was notably decreased (P < 0.05)." (PMID 32396525, 2020). "Similarly, Thy-1 positive lung fibroblasts are resistant to TGF-β activation induced lung fibrosis, implicating possible role of Thy-1 in suppressing αvβ6 mediated TGF-β activation." (PMID 30859101, 2019). "Zhu’s team, in a mouse model of pulmonary fibrosis induced by lipopolysaccharide (LPS), demonstrated that butyrate pretreatment could inhibit ThY-1 gene expression and pulmonary fibrosis by inhibiting histone deacetylase (HDAC) activation and histone H4 deacetylation." (PMID 36274689, 2022). "Therefore, we speculated that miR-214 might inhibit THY1 to mediate pulmonary fibrosis, and carried out further experiments to test this hypothesis." (PMID 32396525, 2020). "When Thy-1 (CD90) was overexpressed or integrin β3 was inhibited, LPS-induced autophagy inhibition and lung fibrosis were prevented." (PMID 36747131, 2023). "Msln−/− mice were protected by ≈50% from bleomycin-induced lung fibrosis as compared with wild-type mice, with reduced activation of Col-GFP+Thy1+ lung fibroblasts." (PMID 36358290, 2022). "To further verify the implications of the YY1/HSF1/miR-214/THY1 axis in IPF development, we used bleomycin to induce a mouse pulmonary fibrosis model." (PMID 32396525, 2020). "Thy1 is silenced in lesional fibroblasts in IPF, and its expression in murine lung fibroblasts is decreased with progression of experimental bleomycin induced lung fibrosis." (PMID 36358290, 2022). "For instance, during idiopathic pulmonary fibrosis, fibroblasts lacking Thy-1 have increased proliferation and decreased myofibroblast differentiation markers." (PMID 35186924, 2022). "Accumulation of Thy1-negative (Thy1−) myofibroblasts was shown in the lungs of humans with idiopathic pulmonary fibrosis (IPF) and of bleomycin-treated mice." (PMID 26300593, 2015). "A growing body of research suggests that the absence of Thy-1 in fibroblasts correlates with a more fibrotic phenotype in vitro and in vivo, such as in the bleomycin-induced pulmonary fibrosis model and human IPF." (PMID 23305530, 2013). "Thy-1, a cell-surface glycoprotein presents on normal lung fibroblasts, is absent from the fibroblastic foci of idiopathic pulmonary fibrosis (IPF)." (PMID 23305530, 2013). "Immunohistochemical analyses of human lung sections reveal that fibroblasts within fibroblastic foci of idiopathic pulmonary fibrosis do not express Thy-1, whereas most fibroblasts from normal lungs are Thy-1+." (PMID 20657842, 2010). "In humans with idiopathic pulmonary fibrosis, no Thy-1 staining was seen in fibroblastic foci." (PMID 26495280, 2015). "Because Thy1 is normally expressed on murine lymphocytes, it is possible that the severe lung fibrosis following bleomycin IT that develops in Thy1-null mice is not due to changes in fibroblast Thy1 expression but rather is due to changes in lymphocyte function." (PMID 26300593, 2015).
lung fibrosis (continued). "As a paradigm, patients with idiopathic pulmonary fibrosis, a disease with pathologic features of chronic inflammation, demonstrate an absence of Thy-1 immunoreactivity within areas of fibrotic activity (fibroblast foci) in contrast to the predominant Thy-1 expressing fibroblasts in the normal lung." (PMID 20657842, 2010). "Interestingly, fibroblasts show reduced Thy-1 expression in areas of active fibrogenesis in human idiopathic pulmonary fibrosis, and in vitro experiments have shown that the lack of Thy-1 expression in fibroblasts is enough to induce myofibroblast differentiation on soft matrix substrates." (PMID 35186924, 2022). "Thus, absence of Thy1 in myofibroblasts may facilitate their faster proliferation, accumulation, and collagen production and therefore increase lung fibrosis." (PMID 26300593, 2015).
melanoma (38 papers, 2013 to 2025). A malignant, usually aggressive tumor composed of atypical, neoplastic melanocytes. "Conversely, overexpression of PIR mRNA was associated with weaker LUM and THY-1 gene expression in transfected melanoma cells relative to the control cells." (PMID 37308689, 2023). "In particular, in anti-PD-1 treated melanoma patients, both high Thy1 and high FAP cell counts are associated with increased overall survival, whereas SMA cell count shows negative associations with patient outcome and survival." (PMID 34067929, 2021). "On the other hand, THY-1 is a protein implicated in the endothelium transvasation of melanoma cells during metastasis spreading." (PMID 32503139, 2020). "Thy-1 (CD90), a cell adhesion molecule expressed in activated endothelial cells, has been implicated in melanoma metastasis by binding to integrins present in cancer cells." (PMID 33511115, 2020). "Because Thy-1 has also been implicated in melanoma metastasis by binding to integrins present in cancer cells, we performed the TEM assay in B16F10 melanoma cells." (PMID 33511115, 2020). "Thy-1 is additionally implicated in melanoma metastasis by binding to αVβ3 Integrin present in cancer cells, both in vitro and in vivo." (PMID 33511115, 2020). "Thus, the generation of transgenic mice with the S901 mutation in mGluR5 in the Thy1 promoter region can be used to investigate the role of the receptor in melanoma." (PMID 36817470, 2023). "In the case of melanoma, the following activation markers should also be noted: osteonectin, desmin, periostin, cluster of differentiation 90/thymus cell antigen 1 (CD90/THY1), and neuron-glial antigen-2 (NG2)." (PMID 40725022, 2025). "For example, Thy-1 expressed on activated microvascular endothelial cells interacts with αvβ3 integrin expressed on melanoma cells to mediate cancer cell invasion." (PMID 38099295, 2023). "The αvβ3 integrin/Thy-1 interaction was additionally extended to other integrins, such as αxβ2 and αMβ2 in leukocytes, and α5β1 in melanoma cells [reviewed in]." (PMID 38099295, 2023). "Remarkably, integrins and syndecan 4 form a trimolecular complex with Thy-1, where two triads have been reported: α5β1/Thy-1/syndecan 4 in melanoma/endothelial cells and αvβ3/Thy-1/syndecan 4 in a neuron/astrocyte model." (PMID 35186924, 2022). "In fact, the triple cooperation between Thy-1, syndecan-4, and α5β1 integrin is responsible for mediating the contractility response to mechanosignals in melanoma cells." (PMID 33669066, 2021). "Based on our previous results that implicated RKIP on the migration capability of melanoma cells, we made use of RKIP overexpression to analyze the effect on ZEB1, NTRK2, and THY-1 transcription." (PMID 32503139, 2020). "Another example is the binding of melanoma integrins to the Thy-1-expressing cytokine-activated endothelium, which increases endothelial cell contractility." (PMID 33134319, 2020). "We then tested the involvement of β3 Integrin in Thy-1-induced melanoma cell migration and invasion by transfecting B16F10 melanoma cells with control siRNA or β3 Integrin siRNA, and then stimulating them with Thy-1-Fc." (PMID 33511115, 2020). "The results indicate that intracellular Ca2+ release is a necessary event for melanoma cell migration/invasion mediated by Thy-1, and that melanoma cell migration requires IP3R activation." (PMID 33511115, 2020). "Thy-1 deficient mice showed significantly reduced metastasis sites due to ablation of Thy-1 mediated melanoma cell adhesion on Endothelial cells." (PMID 30859101, 2019). "Thy-1 mediated cell-cell interaction has also been found to be critical for melanoma cell adhesion and metastasis." (PMID 30859101, 2019). "Pretreatment whole tissue sections from 117 melanoma patients treated with anti-PD-1 therapy underwent CAF (Thy1, SMA, FAP) profiling by multiplex immunofluorescence." (PMID 31337426, 2019).
melanoma (continued). "Melanoma cells have also been seen to exploit Thy-1 expressed by vascular endothelial cells for adhesion and subsequent tumor metastasis, presumably through Thy-1- αvβ3 interaction." (PMID 30859101, 2019). "This study examines the clinical significance of cancer-associated fibroblast (Thy1, SMA, FAP) profiles in pretreatment tumor specimens to determine their association with immunotherapy outcome in melanoma." (PMID 31337426, 2019). "Pretreatment whole tissue sections from 117 melanoma patients treated with anti-PD-1 therapy were assessed by multiplex immunofluorescence to detect CAFs defined by Thy1, smooth muscle actin (SMA), and fibroblast activation protein (FAP)." (PMID 31337426, 2019). "It was shown that αvβ3 integrin on melanoma cells interacts with Thy1 on endothelial cells in order to facilitate metastasis." (PMID 27409827, 2016). "It was recently discovered that the endothelial surface molecule Thy-1 (CD90) is important for B16/F10 melanoma cells adhesion to endothelium via αVβ3 integrin, favoring metastasis in an in vivo model." (PMID 26558271, 2015). "It has been demonstrated that endothelial cell Thy-1 interacts with αvβ3 on melanoma cells and αXβ2 as well as αMβ2 on leukocytes and promote the migration of these cells." (PMID 23613866, 2013). "Compared to mGluR5 wild-type, Thy1-mGluR5 S901A mutant mice developed melanoma." (PMID 36817470, 2023). "More specifically, trans-interaction between Thy-1 and integrin, which also involves the heparan sulfate proteoglycan syndecan-4 forms a tri-molecular complex that regulates the adhesion and migration of melanoma cells, blood cells and astrocytes." (PMID 35733855, 2022). "Moreover, the Thy-1-integrin linkage is relevant in melanoma invasion, myocyte transmigration through endothelial cells, and host defense mechanisms." (PMID 33669066, 2021). "Most importantly, silencing of β3 Integrin in melanoma cells (this paper) or injection of wild type B16F10 cells in Thy-1 knock-out mice abolish melanoma lung metastasis in vivo, indicating that disruption of the Thy-1-αVβ3 Integrin interaction precludes melanoma metastases." (PMID 33511115, 2020). "Thus, we evaluated the participation of this signaling pathway in Thy-1-induced melanoma migration and invasion." (PMID 33511115, 2020). "Thus, cell-cell interaction between Thy-1 on activated EC and αVβ3 Integrin on melanoma cells is an essential step in melanoma metastasis." (PMID 33511115, 2020). "Therefore, considering the importance of the Thy-1 and αVβ3 Integrin interaction in melanoma progression, relevant questions are: (i) Is Thy-1-Integrin engagement relevant for the migration of other cancer cells?" (PMID 33511115, 2020). "Furthermore, elevated expression of Thy-1 on blood vessel and lymphatic EC has revealed that Thy-1 participates in hematogenic and lymphogenic metastasis of melanoma cells in vivo." (PMID 33511115, 2020). "An example of such heterophilic interactions is that mediated by the glycosyl-phosphatidylinositol (GPI)-anchored adhesion protein Thy-1 (expressed on many cells including neurons, fibroblasts, thymocytes and cancer cells) with integrins, such as αVβ3 on astrocyte and α5β1 on human melanoma cells." (PMID 33134319, 2020). "We found that these treatments precluded Thy-1-Fc-induced melanoma cell migration and invasion." (PMID 33511115, 2020). "Likewise, syndecan-4 promotes A375 melanoma cells binding to the endothelium by participating of a ternary complex with α5β1 integrins and Thy-1." (PMID 26558271, 2015). "Of interest, THY1 has been shown to have contradictory functions in different tumor types, where it functions as a tumor suppressor in ovarian and nasopharyngeal cancer, yet it promotes migration and metastasis in melanoma and hepatocarcinomas." (PMID 24194916, 2013). "Using an unbiased approach, we investigated the distribution of Lineage-Thy1+ subsets and their relative PD-1 expression within the TME of B16-BL6 murine melanomas." (PMID 37098069, 2023).
melanoma (continued). "First, the role of intracellular Ca2+ increase in melanoma cell migration and invasion was tested by treating B16F10 cells with BAPTA-AM or 2-APB, and then stimulating them with Thy-1-Fc." (PMID 33511115, 2020). "Approximately 5% of cells from secondary melanoma cultures and melanocyte cultures stained with the anti-fibroblast mAb CP28, against CD90/(Thy-1)." (PMID 28264026, 2017). "FSCs isolated from human skin and melanoma biopsies could be readily infected with artLCMV vaccine vectors with the majority of LCMV-NP+ FSCs showing co-expression of CD90 (Thy1) and PDPN." (PMID 34354077, 2021). "So far, adhesion and cell migration induced by the Thy-1-αVβ3 Integrin interaction has not been studied in cancer cells other than melanoma." (PMID 33511115, 2020). "Saalbach and coworkers reported that in primary melanoma, as well as in subcutaneous metastases, the cell adhesion molecule of the immunoglobulin superfamily Thy-1 (CD90) is detectable in EC, but absent in healthy skin and in benign melanocytic skin lesions (nevi)." (PMID 33511115, 2020). "Similarly, OS had significant positive associations with both Thy1 and FAP cell counts, and a negative association with SMA cell count, which were specific to anti-PD-1 treated melanoma patients (all P < 0.003)." (PMID 31337426, 2019).